AKIRIN2 (akirin 2)
Diseases named in the same sentence as AKIRIN2 in open-access papers:
AKIRIN2 is named in the same sentence as 33 diseases in open-access papers, as found by Europe PMC text mining. Sharing a sentence is not in itself a finding about the gene and the disease. The quoted sentences say what the papers report.
glioblastoma (4 papers, 2013 to 2019). The most malignant astrocytic tumor (WHO grade IV). "Akirin2 is upregulated in human primary glioblastomas, and confers chemoresistance to glioblastomas and imatinib resistance to chronic myeloid leukemia." (PMID 30886152, 2019). "Akirin2 knockdown also renders glioblastoma cell lines more prone to cell death, suggesting that Akirin2 is important for cell survival in rapidly dividing cells." (PMID 27871306, 2016). "Here we now showed for the first time that Akirin-2 is expressed in human primary glioblastomas on mRNA and protein level, and is induced upon TMZ treatment." (PMID 26036627, 2015). "Our results showed that, compared with Twist-1, Akirin-2 is the more promising target for RNAi strategies antagonizing Twist-1/Akirin-2 facilitated glioblastoma cell survival." (PMID 26036627, 2015). "Glioblastoma cells containing decreased amounts of Akirin-2 after kd contained increased amounts of cCaspase-3 as determined by the ImageStreamx Mark II technology." (PMID 26036627, 2015). "We found that in glioblastomas, highly malignant brain tumors, Akirin-2 and Twist-1 were expressed in glial fibrillary acidic protein positive tumor regions as well as in tumor endothelial cells and infiltrating macrophages / microglia." (PMID 26036627, 2015). "Furthermore, the FBI1/Akirin2 gene was robustly expressed in rat HCCs, glioblastoma cells, pheochromocytoma cells, and embryonic carcinoma cells, compared with the respective normal tissues." (PMID 24223164, 2013).
glioma (3 papers, 2013 to 2022). A benign or malignant brain and spinal cord tumor that arises from glial cells (astrocytes, oligodendrocytes, ependymal cells). "In addition, AKIRIN2 participates in the regulation of chemotherapy sensitivity of glioma, chronic myelogenous leukaemia, and ovarian cancer." (PMID 36059811, 2022). "In addition, FBI1/Akirin2 suppressed the BCAM promoter activity in a variety of cell lines such as rat glioma C6, Huh7, HeLa and COS-7, by luciferase reporter assay." (PMID 24223164, 2013). "Solid and cultured primary human GBMs, glioma-infiltrating macrophages/microglia (GIMs), human umbilical vein endothelial cells (HUVEC) and five different GBM cell lines were all characterized by distinct Twist-1 and Akirin-2 mRNA expression except for HUVEC, that did not express Twist-1." (PMID 26036627, 2015).
cholangiocarcinoma (2 papers, 2019 to 2022). A carcinoma that arises from the intrahepatic biliary tree (intrahepatic cholangiocarcinoma) or from the junction, or adjacent to the junction, of the right and left hepatic ducts (hilar cholangiocarcinoma). "AKIRIN2 has been shown to be associated with cholangiocarcinoma promoting invasion and angiogenesis." (PMID 35589807, 2022).
hepatoma (2 papers, 2013 to 2016). "Akirin2 is overexpressed in a number of tumor cell lines, and antisense-mediated knockdown of Akirin2 led to growth inhibition and reduced tumorigenicity and metastasis of K2 hepatoma and Lewis lung carcinoma cell lines." (PMID 27871306, 2016).
liver cancer (2 papers, 2022 to 2024). An epithelial or non-epithelial malignant neoplasm that arises from the liver. "AKIRIN2 is necessary for the growth and metastasis of lung cancer and liver cancer and promotes the angiogenesis of gallbladder cancer through interleukin-6 (IL-6)/signal transducer and activator of transcription 3 (STAT3)/vascular endothelial growth factor A (VEGFA)." (PMID 36059811, 2022). "Silencing FBI1/Akirin2 expression leads to increased Lu/BCAM expression, while the overexpression of Lu/BCAM inhibits crucial biological behaviors, such as clone formation, cell migration and invasion in rat liver cancer cells." (PMID 39000374, 2024).
anaplastic thyroid cancer (1 paper, 2020). "Some of these genes may be of particular interesting in the thyroid; for instance, Arid2 was shown to be mutated in poorly differentiated and anaplastic thyroid cancer, and Akirin 2 is emerging as a novel player in the NF-κΒ-driven immune/inflammatory response." (PMID 32961913, 2020).
Ataxia (1 paper, 2016). Ataxia refers to impaired coordination of voluntary muscle movement. "Decreased size, ataxia, and hyperphagia in the few Akirin2 knockouts that survive postnatally." (PMID 27871306, 2016).
brain tumors (1 paper, 2015). "Nevertheless, up to now neither the expression of Akirin in human brain tumors nor the functional role of Akirin-2 and Twist-1 in mediating chemoresistance particularly in GBMs have been investigated." (PMID 26036627, 2015).
Cerebral ischemia (1 paper, 2024). Restriction of arterial blood supply to the brain associated with insufficient oxygenation to support the metabolic requirements of the tissue. "This suggests that the Akirin2‐PTEN signaling pathway may, at least in part, be a potential mechanism underlying the neuroprotective effect of tDCS and ISO in cerebral ischemia/reperfusion injury." (PMID 39267282, 2024). "An important molecule downstream of Akirin2 to induce the effect on cerebral ischemia/reperfusion injury may be PTEN signaling." (PMID 39267282, 2024). "Therefore, Akirin2 may act as a new therapeutic target to prevent and treat cerebral ischemia/reperfusion injury." (PMID 39267282, 2024).
diabetic kidney disease (1 paper, 2025). Progressive kidney disorder caused by vascular damage to the glomerular capillaries, in patients with diabetes mellitus. "Previously, AKIRIN2 gene expression was found to be higher in the tubules of individuals with diabetic kidney disease than in that of healthy individuals." (PMID 41465209, 2025).
ischemia (1 paper, 2024). A hypoperfusion of the BLOOD through an organ or tissue caused by a PATHOLOGIC CONSTRICTION or obstruction of its BLOOD VESSELS, or an absence of BLOOD CIRCULATION. "Subsequently, we explored how intraneuronal ISO mediates the reduction of neuronal death post‐ischemia–reperfusion injury through Akirin2." (PMID 39267282, 2024).
ischemic stroke (1 paper, 2024). A stroke disorder caused by obstruction of blood flow to the brain, due to thrombotic (local blood clot formation) or embolic (due to a blood clot or other material traveling from another site) event. "tDCS treatment enhances the neuroprotective effects of ISO preconditioning on ischemic stroke by inhibiting oxidative stress and activating Akirin2‐PTEN signaling pathway, highlighting potential of combination therapy in ischemic stroke." (PMID 39267282, 2024). "Furthermore, we confirmed that Akirin2 was the upstream of PTEN in ischemic stroke, as evidenced by an increased expression of PTEN mRNA and protein after Akinrin2 knockdown in primary cortical neurons subjected to O/R injury." (PMID 39267282, 2024). "However, although we determined the possible neuroprotective effects of the Akirin2‐PTEN signaling pathway on recovery of ischemic stroke, the detailed mechanisms for the signaling to induce these effects were not determined." (PMID 39267282, 2024). "Our results suggest that rat primary neurons exhibited a significant decrease in Akirin2 expression after stroke, indicating that Akirin2 may be involved in the development of ischemic stroke." (PMID 39267282, 2024). "The role of Akirin2 in ischemic stroke is yet to be explored." (PMID 39267282, 2024). "Moreover, we report for the first time that the nuclear protein Akirin2 plays an important role in the pathogenesis of ischemic stroke and tDCS in combination with ISO preconditioning‐mediated neuroprotective effects." (PMID 39267282, 2024). "Transcranial direct current stimulation treatment alleviates oxidative stress and activates Akirin2‐PTEN signaling pathway, and enhances the neuroprotective effect of isoflurane pretreatment on ischemic stroke, highlighting the potential of combination therapy for ischemic stroke." (PMID 39267282, 2024).
microcephaly (1 paper, 2016). A congenital or acquired developmental disorder in which the circumference of the head is smaller than normal for the person's age and sex. "Akirin2 may thus be a newly-implicated player in various forms of microcephaly and other malformations of cortical development." (PMID 27871306, 2016). "The vast majority of Akirin2 mutants do not survive past birth, and exhibit extreme microcephaly, with little dorsal telencephalic tissue and no recognizable cortex." (PMID 27871306, 2016). "In the absence of Akirin2, mice exhibit extreme microcephaly, with nearly complete absence of any cortical tissue, due to disrupted cell proliferation, reduced neuron production, and massive apoptosis of both neurons and progenitors." (PMID 27871306, 2016).
promyelocytic leukemia (1 paper, 2021). "In the present study, we focused on the Akirin2 regulome and interactome in model human Caucasian promyelocytic leukemia HL60 cells to advance the knowledge of the function of this highly conserved regulatory cofactor." (PMID 34291801, 2021). "In the present study, we focused on the human Akirin2 regulome and interactome in neutrophil-like model human Caucasian promyelocytic leukemia HL60 cells." (PMID 34291801, 2021).
Stomach adenocarcinoma (1 paper, 2022). "In this study, AKIRIN2 is highly expressed in Gastric adenocarcinoma through bioinformatics analysis based on Stomach adenocarcinoma samples data from The Cancer Genome Atlas." (PMID 35589807, 2022). "The results showed that AKIRIN2 is an effective biomarker of Gastric adenocarcinoma prognosis, which can guide chemotherapy and immunotherapy and clarify the progress of Gastric adenocarcinoma promoted by immune microenvironment." (PMID 35589807, 2022).
virus infection (1 paper, 2022). "These circRNAs were annotated to 21 parental genes, of which seven had functions relating to immune response or virus infection, such as CD2AP, QKI, and AKIRIN2." (PMID 35049781, 2022).
tumor (7 papers, 2015 to 2024). "Univariate and multivariate Cox regression analyses assessed the correlation between OS and clinical characteristics and demonstrated that the level of AKIRIN2 and tumor stage were two risk factors affecting the survival of GA patients." (PMID 35589807, 2022). "We found that high Akirin2 expression was closely associated with late tumor stages (P = 0.024) and positive lymph node invasion (P = 0.047)." (PMID 30886152, 2019). "Considering VEGFA functions as a key regulator in the process of tumor angiogenesis, we then explored whether there was an association between the expression of Akirin2 and VEGFA." (PMID 30886152, 2019). "Next, we explored the possibility of AKIRIN2 as a potential biomarker of GA prognosis and analyzed the interaction between tumor immune infiltration and AKIRIN2 expression in GA." (PMID 35589807, 2022). "We collated the clinical data of the two groups, including gender, age, tumor grade, and tumor stage, to evaluate the correlation between clinical parameters and AKIRIN2." (PMID 35589807, 2022). "The univariate Cox regression forest plot demonstrated that tumor stage III, IV (P = 0.013), and the level of AKIRIN2 (P = 0.031) were identified as independent risk factors to affect the OS of GA patients." (PMID 35589807, 2022). "Conversely, tumor growth and tumor weight in the Akirin2-overexpressed group were significantly higher compared with the empty vector group." (PMID 30886152, 2019). "The results showed that overexpression of Akirin2 efficiently restored the pre-miR-490-3p-medieted tumor-suppressive effects, as represented by enhanced cell migration and angiogenesis of CCA cells." (PMID 30886152, 2019). "An in vivo tumor model further validated the oncogenic effect of Akirin2 on CCA cell growth, metastasis, and angiogenesis." (PMID 30886152, 2019). "Complementary, since Twist-1 is well known in mediating progression of various tumors, an involvement of Akirin-2 in tumor progression seems to be rather likely." (PMID 26036627, 2015). "The findings reflected that AKIRIN2 is highly expressed in tumor samples." (PMID 35589807, 2022). "Our results showed that Akirin2 was overexpressed in human CCA cell lines and tumor tissues and that Akirin2 overexpression could promote CCA cell proliferation, migration, invasion, and angiogenesis both in vivo and in vitro." (PMID 30886152, 2019). "Here, we reported that miR-490-3p could function as a tumor suppressor by targeting the 3′-UTR of Akirin2 mRNA to inhibit CCA cell migration and tube formation." (PMID 30886152, 2019). "Thus, a tumor-promoting function of Akirin-2 is obvious and now clearly addressed also in the human system." (PMID 26036627, 2015). "Moreover, Akirin2 levels were positively correlated with VEGFA expression in CCA tissues, indicating that Akirin2 might promote tumor angiogenesis in human CCA." (PMID 30886152, 2019). "The 14-3-3β-binding protein FBI1/Akirin2 sustains ERK1/2 activation by suppressing MKP-1 (MAPK phosphatase) transcription, fostering tumor genesis and metastasis." (PMID 39000374, 2024). "Consistently, we found that Akirin2 overexpression upregulated, whereas endogenous Akirin2 knockdown eliminated VEGFA expression and angiogenesis through the IL-6/STAT3 signaling pathway, and thus facilitated tumor growth, invasion, and metastasis." (PMID 30886152, 2019). "To investigate whether Akirin2 possessed a tumor-promoting function in CCA, we stably downregulated Akirin2 in high Akirin2-expressing CCLP1 and RBE cells using a lentivector carrying short hairpin RNA (shRNA)." (PMID 30886152, 2019). "As Akirin2 knockdown impaired CCA cell proliferation in vitro and in vivo, we hypothesized that Akirin2 downregulation could attenuate tumor angiogenesis." (PMID 30886152, 2019).
tumor (continued). "We found that tumors derived from Akirin2 knockdown cells grew more slowly, and the final tumor weight was markedly lower in the Akirin2 knockdown group than that in the negative control (sh-NC) group, which was consistent with the results in vitro." (PMID 30886152, 2019). "Akirin2, but not Akirin1, was also studied in the context of tumor promotion." (PMID 31767636, 2020).
cancer (3 papers, 2019 to 2023). A tumor composed of atypical neoplastic, often pleomorphic cells that invade other tissues. "Recently, a screen for regulators of the levels of the transcription factor MYC by de Almeida and colleagues identified an unexpected function for human AKIRIN2 as a regulator of the turnover of a subset of nuclear proteins in human cancer cells." (PMID 37767001, 2023). "In addition, the akir-1 null mutants display a developmental defective but viable phenotype, whereas the AKIRIN2 knockout results in apoptosis of human cancer cells." (PMID 37767001, 2023). "Also, Genomics of Drug Sensitivity in Cancer database was utilized to verify the correlation between AKIRIN2 expression level and the efficacy of chemotherapy and immunotherapy." (PMID 35589807, 2022). "To explore whether Akirin2 was involved in cancer metastasis, we conducted wound scratch and Transwell experiments to examine the impact of Akirin2 on modifying CCA cell motility." (PMID 30886152, 2019). "As epithelial–mesenchymal transition (EMT) markers are key regulators in cancer cell migration and metastasis, we asked whether Akirin2 affected the EMT process in CCA cells." (PMID 30886152, 2019). "In vertebrates, de Almeida and colleagues recently discovered human AKIRIN2 as a proteasome binding protein essential for the nuclear localization of proteasomes in cancer cell lines, but whether this is true for a broad range of cell types as found in an entire organism remains to be elucidated." (PMID 37767001, 2023). "However, the role of AKIRIN2 in human diseases, especially cancer, is still poorly studied." (PMID 35589807, 2022). "Based on the genomics of drug sensitivity in cancer (GDSC) database, the response of patients with high- and low-expression of AKIRIN2 to chemotherapy drugs was explored." (PMID 35589807, 2022).
infection (3 papers, 2019 to 2024). The state of being infected such as from the introduction of a foreign agent such as serum, vaccine, antigenic substance or organism. "At 6 h after infection, the expression of Akirin2, a nuclear protein that plays an important role in the innate immune response and embryonic development, was 1.6 times higher than in the uninfected group." (PMID 38759153, 2024). "Future experiments should be directed to functionally characterize how Akirin2–histone H3.1 interaction regulates transcription and identified BPs at the transcriptome/regulome level and in response to stimuli such as pathogen infection." (PMID 34291801, 2021). "Subolesin (SUB, also known as 4D8) is the functional homolog of Akirin2 involved in the regulation of development and innate immune response, and a proven protective antigen for the control of ectoparasite infestations and pathogen infection." (PMID 30881925, 2019).
neurodegenerative disease (1 paper, 2024). A disorder of the central nervous system characterized by gradual and progressive loss of neural tissue and neurologic function. "A recent study suggests an essential role of Akirin2 in maintaining healthy neurons during cortical maturation and that Akirin2 dysfunction may lead to neurodegenerative diseases." (PMID 39267282, 2024).
neurological disorders (1 paper, 2024). "The nuclear protein Akirin2 is broadly expressed in the CNS and closely associated with the control of cell proliferation and differentiation, which is emerging as a critical regulator in neurological disorders." (PMID 39267282, 2024). "The emerging evidence suggests a correlation between Akirin2 dysfunction and neurological disorders." (PMID 39267282, 2024).
AKIRIN2 also shares sentences with these, for which no sentence is quoted: autism (1 paper); chronic myelogenous leukaemia (1); developmental delay (1); embryonic carcinoma (1); gallbladder cancer (1); gastric cancer (1); Lewis lung carcinoma (1); lung carcinoma (1); neurodevelopmental disorder (1); ovarian carcinoma (1); pheochromocytoma (1); Stroke (1).